KRAS (KRas proto-oncogene, GTPase)
Diseases named in the same sentence as KRAS in open-access papers (continued):
Sharing a sentence is not in itself a finding about the gene and the disease.
urothelial papillomas of the bladder (1 paper, 2020). "Varied papillary lesions, including intraductal papillary mucinous neoplasms of the pancreas and urothelial papillomas of the bladder, also have frequent KRAS mutations." (PMID 33023600, 2020).
Wolffian tumors (1 paper, 2022). "Moreover, Wolffian tumors have not been shown to harbor any pathogenic KRAS mutation." (PMID 35204416, 2022).
yolk sac tumor (1 paper, 2020). A non-seminomatous malignant germ cell tumor composed of primitive germ cells. "An analysis of 87 MOGCTs identified recurrent mutations in KIT and KRAS, along with frequent focal amplifications of PIK3CA and AKT1 in yolk sac tumors." (PMID 32455595, 2020).
tumor (7,803 papers, 1989 to 2026). "Molecular analysis of the liver metastasis revealed a KRAS mutation, in contrast to the primary tumor." (PMID 42130526, 2026). "The divergent fates of mutant and wild-type KRAS under hypoxic stress highlight isoform-specific regulatory mechanisms underlying tumor progression." (PMID 41531732, 2026). "This concordance between organoid models and primary tumor cells underscores the robustness of transcriptional network activation as a hallmark feature of KRAS-mutant MSS CRC." (PMID 41362735, 2026). "KRAS mutated LUADs are frequently associated with tobacco exposure, elevated PD-L1 expression, high tumor mutational burden, and an inflamed tumor microenvironment." (PMID 41526435, 2026). "Tumor cells, particularly those with KRAS or BRAF mutations, rely heavily on glycolysis for energy production, leading to overexpression of GLUT1 and SVCT2." (PMID 41403402, 2026). "Previous studies reported that KRAS-mutant CRC patients are associated with an immunosuppressive tumor microenvironment (TME)." (PMID 41362725, 2026). "Eligible studies included those measuring plasma KRAS mutations and/or reporting variant allele frequency, tumour fraction, or multi-locus aggregate metrics." (PMID 42073641, 2026). "In human CRC, it is notoriously difficult to deconvolute the order of early clonal driver events such as APC and KRAS mutations from sequencing data derived from bulk tumour samples." (PMID 41339549, 2026). "This study aimed to evaluate the association between primary tumor sidedness, KRAS/NRAS/BRAF mutational status, and VTE occurrence in patients with mCRC treated in the outpatient setting." (PMID 41751211, 2026). "Current knowledge indicates how mevalonate pathway dysregulation intersects with other metabolic networks and oncogenic drivers, such as KRAS mutations, to facilitate tumor growth, metastasis, and therapeutic resistance." (PMID 41550359, 2026). "Tumor purity and KRAS mutation status were significantly associated with the glycolytic group in two out of three cohorts, indicating partial cohort-dependent relationships." (PMID 41554705, 2026). "Molecular testing revealed a KRAS p.G12V activating mutation.DiscussionMLA has a broad differential diagnosis and is often misinterpreted as other neoplasms." (PMID 41989344, 2026). "NRAS mutations typically arise at a later stage of tumor progression and are often observed either alone or in combination with a KRAS mutation during tumor recurrence." (PMID 41488286, 2026). "We also emphasize the importance of modifiable risk factors that function as tumor promoters of initiated pancreatic cells harboring KRAS mutations." (PMID 41484057, 2026). "Recognition of autologous tumor cells and tumor-specific mutations, including mutations in KRAS and mitochondrial UQCRFS1 (D145V), was assessed using MHC class I and II restriction assays." (PMID 42121899, 2026). "In the tumor center, similar but weaker patterns are seen, and KRAS mutation is additionally linked to increased regulatory T cell (FoxP3+) infiltration, further supporting an immunosuppressive phenotype." (PMID 41596586, 2026). "The Genetic And Morphological Evaluation (GAME) score was utilized to risk stratify patients based on KRAS status, carcinoembryonic antigen levels, primary tumor lymph node metastasis, tumor burden score, and extrahepatic disease." (PMID 41708935, 2026). "Recently, it has been reported that a novel pan-RAS translation inhibitor 15a also suppresses the proliferation of KRAS mutation-driven tumor cells." (PMID 41362725, 2026).
tumor (continued). "This effort identified LS-1-2, an acridine derivative demonstrating potent anti-tumor and anti-metastatic activity against KRAS-mutated CRC in both in vitro and in vivo models." (PMID 41362735, 2026). "Immunocompromised mice transplanted with KRAS mutated tumor cells were treated daily with afatinib (20 mg/kg), tozasertib (75 mg/kg), or the combination starting two days after engraftment and continuing for 19 days." (PMID 41526435, 2026). "Further, it was associated with activated oncogenic and chemoresistance pathways, multi-drug resistance to standard therapies, higher tumor mutational burden and increased KRAS mutation frequency." (PMID 41854891, 2026). "In the context of STK11 loss, tumor cells exploit multiple mechanisms to evade KRAS G12Ci therapeutic pressure." (PMID 41541668, 2026). "Additional variables analyzed included hypoxia score, KRAS mutation status, tumor purity, molecular subtype, and tumor stage." (PMID 41554705, 2026). "Over 90% of PDAC patients harbor KRAS gene driver mutations, which promote tumor proliferation, invasion, and immunosuppression of the tumor microenvironment through constitutive activation of downstream RAF/MEK/ERK and PI3K/AKT/mTOR signaling pathways." (PMID 41942368, 2026). "SMARCA4 mutations, similar to KRAS mutations, are often smoking-associated and linked to high tumor mutation burden." (PMID 41541668, 2026). "In PDAC, we found that DKK3 loss facilitates tumor‐initiating functions in acinar cells, promoting their transformation into ductal structures, even in a KRAS wild‐type context." (PMID 41147409, 2026). "Specifically, the activation of the MEK-ERK-AP1 pathway by mutated KRAS induces tumor cells to secrete interleukin-10 (IL-10) and transforming growth factor-β1 (TGF-β1)." (PMID 41362725, 2026). "A significant decrease of 60% in KRAS G12S expression was observed in a mouse model, resulting in regression of tumour burden while causing minimal toxicity to healthy tissues." (PMID 39820726, 2025). "Shared neoantigens (KRAS G12D mutation) or tumor-associated antigens (telomerase, survivin) can be common in specific patient populations." (PMID 41567982, 2025). "Clinical trials targeting D-1553 are also ongoing and have shown promising anti-tumor activity in patients with NSCLC with KRAS G12C mutations in phase I studies." (PMID 40303413, 2025). "A Kirsten rat sarcoma viral oncogene homolog (KRAS) V14I mutation (c.40G>A p.V14I @ 19% variant allele frequency (VAF)) was identified on genetic next-generation sequencing of the tumor cells." (PMID 40012695, 2025). "Reduced VEGF expression and decreased density of CD31+ endothelial cells in NE-deficient KRAS mutant mice, suggesting that neutrophil NE promotes tumor angiogenesis." (PMID 41254689, 2025). "The frequency of KRAS mutations according to tumor type differed from that reported in previous studies." (PMID 40499463, 2025). "Therapies targeting the KRAS mutation aim to silence mutant KRAS mRNA, preventing its translation and thus inhibiting tumor progression." (PMID 40805153, 2025). "It is noteworthy that recent research suggested that KRAS mutations enhance the activity of OXPHOS in tumor cells." (PMID 39932442, 2025). "Our results suggest that gaining KRAS mutations allows these tumours to evolve more rapidly, acquiring a set of smoking-associated key alterations, with less need for genomic instability to progress." (PMID 41509216, 2025). "A later study detected KRAS mutations in 23% of FAP tumor samples and somatic APC mutations in 69% of the patients." (PMID 41488735, 2025). "Preclinical and early clinical studies demonstrate that dual inhibition—such as combining MEK and PI3K inhibitors—can induce synergistic apoptosis and tumor regression, particularly in tumors harboring KRAS, BRAF, or PIK3CA mutations." (PMID 40943615, 2025).
tumor (continued). "The biomarkers investigated included Programmed death-ligand 1 (PD-L1), Epidermal growth factor receptor (EGFR), Anaplastic lymphoma kinase (ALK), Kirsten rat sarcoma (KRAS), and others associated with tumor proliferation and therapeutic response." (PMID 40078179, 2025). "The tumor was KRAS-mutated, with metastasis to two peritumoral regional lymph nodes (Dukes stage C), but surgical margins were free of neoplastic involvement." (PMID 39926284, 2025). "Among the 18 tumours with pathogenic KRAS mutations, KRASG12 substitutions were most frequent (n = 14, 78%) and included 6 KRASG12D, 5 KRASG12V, 2 KRASG12S and 1 KRASG12C substitutions." (PMID 41115454, 2025). "KRAS mutations are known to increase the expression of programmed death-ligand 1 (PD-L1) within tumor cells, enabling the tumor to shun the immune system for detection and subsequent destruction." (PMID 40012626, 2025). "As a key regulator of the RAS/MAPK signaling pathway, KRAS controls cell proliferation and differentiation; mutation in the gene results in persistent activation of this pathway, thereby driving tumor progression." (PMID 40499463, 2025). "The presence of KRAS mutations is often associated with aggressive tumor phenotypes and resistance to therapy, which underlines the urgent need for models that can accurately replicate these mutations for research and therapeutic development." (PMID 39786607, 2025). "KRAS mutations have been shown to drive high lactate production, resulting in its significant accumulation within the tumor microenvironment." (PMID 40303413, 2025). "It has been reported that the presence of undetectable micrometastases in the liver in patients with KRAS mutation predisposes them to R1 resection with parenchymal preservation and to reduced OS in patients with tumor recurrence in the residual liver." (PMID 39873424, 2025). "In NSCLC, tumor-derived exosomes from patients with any KRAS mutation type induced peripheral blood CD4+ T cell differentiation into Tregs." (PMID 40611261, 2025). "Although KRAS mutations are highly prevalent and play a pivotal role in tumor growth and survival, KRAS was long regarded as “undruggable” due to its high affinity for guanosine triphosphate (GTP) and the absence of accessible binding pockets." (PMID 41155693, 2025). "After the terms ‘serrated pathway’ and ‘SAC’ were defined, more KRAS mutations were found in these neoplasms." (PMID 40572720, 2025). "The KRAS mutation pathway, which is frequently activated in tumor cells, accounts for enhanced apoptosis inhibition, migration, and proliferation." (PMID 40445912, 2025). "The epidemiological distribution of KRAS G12C mutations varies significantly across different tumor types, reflecting the complex interplay between genetic susceptibility, environmental exposures, and tissue-specific oncogenic pathways." (PMID 40940900, 2025). "SCH44342, a non-peptidic FTI, inhibited RAS processing with nanomolar potency, while Lonafarnib (SCH66336) demonstrated strong selectivity and effectively suppressed tumor growth in KRAS-mutated mouse models." (PMID 40597785, 2025). "For example, vaccines loaded with peptides from commonly mutated genes, such as KRAS, or tumor lysates have induced tumor-specific immune responses." (PMID 40013133, 2025). "First, during tumour initiation, driver mutations (such as KRAS^G12D or EGFR mutations) can only efficiently induce lesion formation in specific progenitor‐like or intermediate ‘damage/plasticity’ states." (PMID 40847555, 2025). "First, KRAS-mutant tumors typically exhibit a higher tumor mutational burden (TMB) generating more neoantigens which can be captured by antigen presenting cells (APC)." (PMID 40809430, 2025).
tumor (continued). "By activating multiple downstream signaling pathways, including MAPK, PI3K/AKT, and RalGDS, KRAS mutations facilitate tumor proliferation, migration, and immune evasion." (PMID 40510156, 2025). "when combined oHSV with PD-1 blockade and MEK inhibition, they found a remarkably synergistic therapeutic efficacy in vivo for BRAF wt/KRAS-mutated tumor models." (PMID 40248194, 2025). "Tregs, tumor‐associated macrophages (TAMs), and myeloid derived suppressive cells (MDSCs) were the primary immune suppressor cell populations enriched in KRAS mutant tumors." (PMID 40485603, 2025). "Both the presence of a KRAS mutation and high mRNA expression levels of KRAS in tumor tissue have been associated with worse outcome." (PMID 40596921, 2025). "This is further supported by the fact that KRAS G12V degradation causes an increase in the number of macrophages with the M2 phenotype, which is active in tumor promotion, and a specific number of macrophages with the M1 phenotype, which is antitumor." (PMID 40805153, 2025). "It has been demonstrated that oncogenic KRAS is released by ferroptotic tumor cells, which drives tumor-associated macrophage polarization." (PMID 39810420, 2025). "Synthetic lethality occurs when the inhibition of a secondary pathway in a tumor harboring a specific mutation (e.g., KRAS) results in cell death." (PMID 40361439, 2025). "KRAS G12C mutations represent a niche but important target in oncology, with implications across several tumor types." (PMID 40940900, 2025). "KRAS mutations in LUAD, particularly KRAS-G12C, are closely associated with elevated PD-L1 expression and an immunosuppressive tumor microenvironment." (PMID 40849659, 2025). "The following section provides a detailed examination of how KRAS mutations interact with and impact the tumor microenvironment via immune cells, chemokines and cytokines." (PMID 39806421, 2025). "Tumor cells attain these metabolic alterations by exerting increased dependency on certain oncogenes, primarily mediated by oncogenic KRAS, mutated in approximately 90% of PDAC cases." (PMID 40090587, 2025). "For instance, in glioblastoma, exosomes delivering CRISPR/Cas9 tools targeting mutant KRAS G12C have demonstrated the ability to knock out the mutant allele, reinstating the tumor’s temozolomide resistance." (PMID 40843170, 2025). "The tumor suppressive effect of wildtype KRAS protein in KRAS mutated tumors is caused by a dimerization between a wildtype and a mutated molecule." (PMID 40596921, 2025). "Each component showed the same type of KRAS mutation (p.G12V) and was considered to originate from a single primary tumor in the pancreas." (PMID 40134936, 2025). "KRAS mutations lead to persistent signaling, uncontrolled cell division, and tumor progression, emphasizing the need for precise detection strategies and targeted therapeutics." (PMID 41514544, 2025). "This figure illustrated the impact of oncogenic KRAS mutations on the tumor metabolic and stromal microenvironment and its related tumor cell metabolism." (PMID 40485603, 2025). "In recent years RDD has been recategorized as a neoplastic disease, one-third of patients have been identified with mutually exclusive Kirsten Rat Sarcoma viral oncogene homolog (KRAS) and MAP2K1 mutations." (PMID 38376733, 2025).